SIRT6 (sirtuin 6)
Diseases named in the same sentence as SIRT6 in open-access papers (continued):
Sharing a sentence is not in itself a finding about the gene and the disease.
chronic kidney disease (9 papers, 2017 to 2025). Impairment of the renal function secondary to chronic kidney damage persisting for three or more months. "Researchers have reported that both Sirt3 and Sirt6 are involved in vascular calcification caused by chronic kidney disease and aging." (PMID 40523615, 2025). "In chronic kidney disease, Runx2 is deacetylated by SIRT6 to inhibit osteogenic trans differentiation of vascular smooth muscle cells." (PMID 39199205, 2024). "Furthermore, SIRT6 has been shown to protect the osteogenic transdifferentiation of vascular smooth muscle cells through RUNX2 in chronic kidney disease." (PMID 35249460, 2022). "SIRT6 has a protective role in patients with chronic kidney disease (CKD)." (PMID 34793336, 2022). "In addition to its direct effects on podocytes, maintained expression of Sirt6 may protect against podocyte dysfunction and injury by regulating inflammation, a key player in the development and progression of chronic kidney diseases." (PMID 28351995, 2017). "In a study of chronic kidney disease (CKD), overexpression of SIRT6 was found to activate the NRF2/HO-1 pathway." (PMID 40258841, 2025). "In a mouse model of chronic kidney disease, treatment with BMMSC-derived exosomes inhibited high-phosphate-induced aortic calcification and ameliorated renal and vascular function via the sirtuin 6 (SIRT6)–high mobility group box 1 deacetylation pathway." (PMID 37509145, 2023).
diabetic nephropathy (9 papers, 2015 to 2025). "Podocyte-specific Sirt6 deficiency exacerbates diabetic nephropathy and adriamycin-induced nephropathy by inhibiting Notch1 and Notch4 transcription through regulation of histone H3K9 acetylation." (PMID 35563783, 2022). "A variety of studies using human renal samples underlying the correlation between Nampt/Sirt6 /TIMP-1 and diabetic nephropathy have been reported, which includes the important roles of these molecules mainly in the middle to late stages of DN." (PMID 38587753, 2024). "Podocyte-specific deletion of Sirt6 exacerbates podocyte injury and proteinuria in two independent mouse models, diabetic nephropathy, and adriamycin-induced nephropathy." (PMID 28871079, 2017). "Additionally, recent studies have revealed that the Nampt-Sirt6 axis was critical in extracellular matrix remodeling during diabetic nephropathy." (PMID 40635752, 2025). "Further studies are needed to uncover whether Sirt1/Claudin-1 is important in the early stages and whether Nampt/Sirt6/TIMP-1 is significant in the middle to late stages of human diabetic nephropathy, similar to that in murine models." (PMID 38587753, 2024). "Moreover, overexpression of Sirt6 facilitated M2 macrophage polarization and ameliorated the progression of diabetic nephropathy." (PMID 35842903, 2022).
acute kidney injury (8 papers, 2021 to 2025). Sudden and sustained deterioration of the kidney function characterized by decreased glomerular filtration rate, increased serum creatinine or oliguria. "The expression of SIRT6 decreases during aging, and current evidence suggests that SIRT6 deficiency may exacerbate acute kidney injury (AKI)." (PMID 39012670, 2024). "In our previous work, we have demonstrated that SIRT6 overexpression improves resistance to acute kidney injury from cisplatin in mice." (PMID 39971710, 2025). "In AKI, autophagy is inhibited and overexpression of Sirt6, which mediates autophagy activation, results in an increased expression of light chain 3 II and an increased lysosome/autophagosome ratio, as well as decreased p62 expression, indicating a protective effect against acute kidney injury." (PMID 38347622, 2024). "HSP increased Nrf2 signalling, SIRT6, NQO1, HO-1 expression, down-regulated SCr, blood urea nitrogen (BUN), MDA, MPO, GSH, SOD, NOX4 expression level, thereby relieving cisplatin-induced acute kidney injury." (PMID 35128104, 2022).
coronary artery disease (8 papers, 2016 to 2025). "Coronary artery diseases are the most common types of cardiac diseases associated with Sirt6 activity." (PMID 37497437, 2023). "It reported that the variants of selected Sirt6 genes, namely, rs350844, rs350846, and rs107251, are involved in the susceptibility to coronary artery diseases in a Chinese population." (PMID 37497437, 2023). "Congestive heart failure and coronary artery diseases are the two most common types of cardiac complications associated with Sirt6 activity." (PMID 33442387, 2020). "Moreover, SIRT6 genetic variants (rs107251, rs352493 and rs3760908) have been reported to associate with severity of coronary artery disease (CAD)." (PMID 27249230, 2016). "In 165 patients with stable coronary heart disease, moderate aerobic training enhanced epoxy-eicosatrienoic acids, activated the FoxO3a/Sirt6 axis, suppressed PCSK9, and ultimately lowered LDL-C despite ongoing statin therapy." (PMID 40861274, 2025). "This notion was exemplified by another study which showed that Sirt6 is tightly related to coronary artery disease as well as its complications." (PMID 37497437, 2023). "Nevertheless, this clinical study strongly indicated that Sirt6 exerts a beneficial effect on the pathogenesis of coronary heart disease." (PMID 37497437, 2023). "In summary, our data echo recent findings that targeting SIRT6 bears translational significance in the intervention of coronary heart disease." (PMID 35246513, 2022). "Several studies implied that Sirt6 may function as a positive regulator in the pathophysiology of coronary heart diseases." (PMID 37497437, 2023). "We observed a decline in SIRT1, SIRT3, and SIRT6 levels, broadly consistent with a ~50% reduction in SIRT1 reported in ischemic heart disease cohorts and a ~35% decline in SIRT3 under pressure-overload conditions." (PMID 41154755, 2025).
diabetic cardiomyopathy (8 papers, 2021 to 2024). Diabetic cardiomyopathy is a disorder of the heart muscle in people with diabetes. "Besides, researchers demonstrated that long-term melatonin treatment mitigates diabetic cardiomyopathy and reduces myocardial susceptibility to I/R insult through preserving mitochondrial quality control via SIRT6-AMPK-PGC1α-AKT signaling pathway." (PMID 37497437, 2023). "Another paper held that Sirt6-KO cardiomyocyte endothelial cells (CMECs) were discovered to exacerbate diabetic cardiomyopathy, as indicated by aggravated perivascular fibrosis, cardiomyocyte hypertrophy, and decreased cardiac function." (PMID 37497437, 2023). "Most recently, literature reported that melatonin-involved activation of Sirt6-related signaling pathway mitigates diabetic cardiomyopathy." (PMID 37497437, 2023). "Impairment of Sirt6 function worsens pathological cellular processes related to the progression of diabetic cardiomyopathy." (PMID 37497437, 2023). "The endothelium-specific knockout of Sirt6 induced EndoMT and increased the expression of proinflammatory cytokines in murine carotid arteries, the involvement of Sirt6-mediated EndoMT in the pathogenesis of diabetic cardiomyopathy had been considered to be critical." (PMID 38789630, 2024). "Therefore, it is possible that Sirt6 impacts diabetic cardiomyopathy pathophysiology." (PMID 37497437, 2023). "SIRT6 and SIRT3 maintain each other’s activity and protect the heart from developing a diabetic cardiomyopathy." (PMID 33806509, 2021). "Consistent with the role of SIRT6 to prevent cardiovascular diseases, a SIRT6 inhibitor, OSS-128267, intensified diabetic cardiomyopathy (DCM)." (PMID 34650436, 2021). "Moreover, SIRT6 and SIRT3 mutually regulate each other’s activity to protect the heart from developing diabetic cardiomyopathy." (PMID 35204314, 2022). "Notably, while SIRT6 and SIRT3 have a myriad of functions that provide health benefits by themselves, it has been found that SIRT6 and SIRT3 also regulate each other’s activity and protect the heart from developing diabetic cardiomyopathy." (PMID 38016059, 2023). "In addition, SIRT6 and SIRT3 interact together to protect against diabetic cardiomyopathy." (PMID 33806509, 2021).
leukemia (8 papers, 2020 to 2025). A malignant (clonal) hematologic disorder, involving hematopoietic stem cells and characterized by the presence of primitive or atypical myeloid or lymphoid cells in the bone marrow and the blood. "SIRT6 activation by DHAs appears to support genomic integrity and DNA repair, providing a protective role in leukemia cells under epigenetic therapy." (PMID 41463311, 2025). "SIRT6 facilitates responses to chemotherapy in leukemia cells, helping them survive treatment-induced stress; EP400 has been shown to be crucial in sustaining the oncogenic potential of MLL leukemia stem cells." (PMID 40700255, 2025). "Accordingly, we tested the effect of DAC on the mRNA and protein expression of SIRT6 in leukemia cells." (PMID 32587297, 2020). "Depletion of SIRT6 compromised DNA repair in leukemia cells and increased their sensitivity to chemotherapy." (PMID 32587297, 2020). "Recent evidence has shown a functional link between SIRT6 and therapeutic response in leukemia." (PMID 41463311, 2025). "Moreover, acetylation modification of SIRT6 in the same family has been proven to be a good target for leukemia therapy." (PMID 38585637, 2024). "To further confirm the observed recombinant SIRT6 activation by the nucleoside analogs DHAs, we tested their effect on the activity of nuclear SIRT6 by incubating them with leukemia cells and measuring SIRT6 activity in the nuclear lysates as described under methods." (PMID 32587297, 2020). "Additionally, we screened their effect on the enzymatic activity of the histone deacetylase sirtuin family (SIRT1, SIRT2, SIRT3, SIRT5 and SIRT6) using both recombinant enzymes and nuclear lysates from leukemia cells." (PMID 32587297, 2020). "SIRT6 activates the PARP1-HMGB1-autophagy pathway and induces chemotherapy resistance in leukemia." (PMID 41463311, 2025). "They significantly increased the enzymatic activity of SIRT6 in both recombinant enzyme assay and in nuclear lysates from leukemia cells without increasing the transcription or protein expression of SIRT6." (PMID 32587297, 2020). "In addition, it was suggested that a synthetic lethal approach, enhancing DNA damage while concomitantly blocking SIRT-6-mediated repair responses through the use of SIRT-6 inhibitors, provides the rationale for the clinical evaluation of SIRT-6 inhibitors in the treatment of leukemia." (PMID 36080416, 2022).
Myocardial fibrosis (8 papers, 2017 to 2025). "Meanwhile, overexpression of SIRT6 reduced myocardial fibrosis as evidenced by a decrease in fibrosis area as well as fibrosis‐related markers." (PMID 38894630, 2024). "In contrast, treatment with SIRT6 prevents Ang II-mediated pathological hypertrophy, myocardial fibrosis, impaired heart function and ultrastructural injury in hypertensive rats." (PMID 29069788, 2017). "Therefore, this study aims to explore whether H2S can improve myocardial cell aging induced by high glucose and myocardial fibrosis in diabetic rats by activating autophagy through SIRT6/AMPK." (PMID 32903815, 2020). "In this study, we found that SIRT6 treatment remarkably potentiated phosphorylated AMPKα levels and subsequently enhanced ACE2 expression, thereby being responsible for attenuation of pathological hypertrophy, cardiac dysfunction, myocardial fibrosis, and injury in hypertensive rats." (PMID 29069788, 2017).
glioblastoma (7 papers, 2019 to 2025). The most malignant astrocytic tumor (WHO grade IV). "SIRT6 plays a crucial role in counteracting the effects of TRF1 knockdown in glioblastoma multiforme cells." (PMID 40710366, 2025). "FOXO3a transcriptionally activates SIRT6 to inhibit the Warburg effect in glioblastoma cells, thereby inhibiting the development of glioblastoma." (PMID 35463332, 2022). "Notably, recent findings revealed that overexpression of SIRT6 can significantly affect glioblastoma cell growth and induce cell injury, resulting particularly evident 48 and 72h after cell seeding." (PMID 32110992, 2020). "Evidence that a 24h treatment of human glioblastoma U87MG cells with 1μM T1AM, SG-1 or SG-2, didn’t affect cell viability while increasing the expression of SIRT6, was provided." (PMID 32110992, 2020). "The study also found that SIRT6 levels were significantly lower in human glioblastoma multiforme tissues compared with adjacent non-tumor tissues, suggesting its role as a tumor suppressor." (PMID 40710366, 2025). "Interestingly, SIRT6, together with SIRT1, coordinated the switch from glucose to FAO during the acute inflammatory response, and transcriptional activation of SIRT6 via FOXO3a inhibited the Warburg effect in glioblastoma cells." (PMID 31849939, 2019).
Glucose intolerance (7 papers, 2013 to 2023). Glucose intolerance (GI) can be defined as dysglycemia that comprises both prediabetes and diabetes. "Interestingly, ectopic expression of SIRT6 in the liver only reduced gluconeogenesis in wild-type but not LTKO mice whereas knockdown of Gck caused glucose intolerance in both wild-type and LTKO mice." (PMID 24015318, 2013). "Regarding the relationship between SIRT6 and metabolic disease, SIRT6 levels increase in rats under the CR condition, and transgenic mice that overexpress SIRT6 are protected against HFD-induced several metabolic impairments, including glucose intolerance." (PMID 30972029, 2019). "However, SIRT6 regulates glucose sensing in pancreatic β cells, and by suppressing SIRT6, in pancreatic β-cells, forkhead box protein O1 (FOXO1) is deacetylated and pancreatic and duodenal homeobox 1 (PDX1) and GLUT2 expression is diminished inducing systemic glucose intolerance." (PMID 35008779, 2021).
lymphopenia (7 papers, 2009 to 2021). Reduction in the number of lymphocytes. "Sirt6-deficient mice displayed dramatic phenotypes including profound lymphopenia, loss of subcutaneous fat, lordokyphosis and low bone marrow density." (PMID 28860594, 2017). "Seminal studies of the role of SIRT6 in aging showed that Sirt6-/- mice displayed a severe progeroid phenotype involving profound lymphopenia and died within the first month of life." (PMID 34946805, 2021). "SIRT6 also plays an important role in T lymphocyte biology, since Sirt6KO mice develop lymphopenia and the availability of NAD+ for SIRT6 activity is pivotal for the regulation of T cell metabolism during the early and late stages of acute inflammation." (PMID 32736564, 2020). "Interestingly, Sirt6-deficient animals develop profound lymphopenia as a result of a cell non-autonomous mechanism, suggesting a possible defect of relevant cytokines or growth factors involved in T cell function." (PMID 19936064, 2009).
rheumatoid arthritis (7 papers, 2019 to 2025). A chronic, systemic autoimmune disorder characterized by inflammation in the synovial membranes and articular surfaces. "Woo and colleagues revealed that myeloid Sirt6 deficiency promotes the pathogenesis of rheumatoid arthritis by accelerating the migration of macrophages from circulation to joint tissues and favoring the M1 type 40." (PMID 35443857, 2022). "A follow-up study showed that in rheumatoid arthritis, SIRT6 inhibition reduces the percentage of Tregs in the peripheral blood and synovial fluid, indicating that SIRT6 has the potential to regulate CD4+ T cell differentiation." (PMID 41049287, 2025). "For instance, inhibiting SIRT6 reduced the percentage of Tregs in the peripheral blood and synovial fluid in rheumatoid arthritis." (PMID 41049287, 2025). "Similarly, NEAT1 inhibits SIRT6 ubiquitination, promoting inflammation in rheumatoid arthritis." (PMID 41268533, 2025).
cardiomyopathy (6 papers, 2022 to 2025). A disease of the heart muscle or myocardium proper. "To further elucidate the role and underlying mechanisms of SIRT6 in DOX-induced myocardial injury, we produced a transgenic mouse model featuring SIRT6 and subsequently created a DOX-induced cardiomyopathy model." (PMID 40093797, 2025). "SIRT6 activation protects against doxorubicin-induced cardiomyopathy by enhancing mitochondrial biogenesis and reducing oxidative stress." (PMID 41425553, 2025). "Among the sirtuin family members, SIRT1, SIRT3 and SIRT6 have attracted much attention as the potential cardioprotective modulators against inflammation, vascular remodelling, cardiomyopathy and the development of atherosclerotic plaques." (PMID 38894630, 2024). "However, the relationship between CIH‐induced cardiomyopathy and SIRT6 remains uncovered." (PMID 38894630, 2024).
cervical carcinoma (6 papers, 2016 to 2025). A carcinoma arising from either the exocervical squamous epithelium or the endocervical glandular epithelium. "TP53BP1, MCM9 (at higher than mean levels), POLR2F and SIRT6 (at lower than mean levels), were associated with an increase in patients experiencing cervical cancer recurrence/progression following postoperative radiation therapy when HPV18 positive, but not HPV16 positive." (PMID 32066835, 2020). "Moreover, increased expression levels of TP53BP1 and MCM9 and decreased expression levels of POLR2F and SIRT6 were found to be specifically associated with a poorer prognosis for HPV18+ (but not HPV16+) cervical cancer patients following PRT." (PMID 32066835, 2020). "SIRT6 overexpression induced apoptosis in HT1080 (fibrosarcoma cells), MEF (mouse embryonic fibroblasts), HeLa (human cervical cancer cells) and HCA2 (human sigmoid colon carcinoma) cells, but not in their non-cancerous/normal counterparts." (PMID 27777384, 2016).
Cognitive impairment (6 papers, 2018 to 2026). Abnormal cognition is characterized by deficits in thinking, reasoning, or remembering. "Strikingly, pharmacological TDO2 blockade, neuronal TDO2 knockdown or mTOR activation reverses synaptic and cognitive deficits in Sirt6 cKO mice." (PMID 42277466, 2026). "To further confirm whether CAPE mitigates cognitive impairment through the Sirt6/Nrf2 signaling pathway, we performed a series of cellular experiments." (PMID 36978961, 2023). "Therefore, we suggested that CAPE pretreatment decreased oxidative stress and favored microglia transforming toward the M2 type via activating the Sirt6/Nrf2 signaling pathway, thereby ameliorating cognitive impairment." (PMID 36978961, 2023). "Moreover, gut dysbiosis and its resultant TMAO overproduction may lead to cognition impairment through inhibition of Sirt6 expression via ROS overproduction." (PMID 31715585, 2019). "Hippocampal excitatory neurons in FGR mice exhibit markedly reduced SIRT6 expression, and SIRT6 conditional knockout in CaMKIIα+ neurons (Sirt6 cKO) recapitulates FGR-induced synaptic and cognitive impairments." (PMID 42277466, 2026). "We hypothesized that niacin supplementation may alleviate WBI-induced behavioral and cognitive impairments by reducing oxidative stress and inflammation through modulation of the SIRT1/CREB/BDNF and SIRT1/SIRT6 signaling pathways." (PMID 40508105, 2025).